CLC (Charcot-Leyden crystal galectin)
Diseases named in the same sentence as CLC in open-access papers (continued):
Sharing a sentence is not in itself a finding about the gene and the disease.
scrapie (1 paper, 2017). A fatal disease of the nervous system in sheep and goats, characterized by pruritus, debility, and locomotor incoordination. "Altogether, these results indicated that both scrapie seeding and the CLC mutations enhanced the in vivo propagation capacities of products generated in vitro in the absence of cofactors or denaturing conditions." (PMID 28910420, 2017).
Stroke (1 paper, 2021). Sudden impairment of blood flow to a part of the brain due to occlusion or rupture of an artery to the brain. "Our findings may contribute to the further elucidation of the mechanism of action of CLC and assist in developing a novel therapeutic strategy for treating clinical stroke." (PMID 34512312, 2021).
type 4 Bartter syndrome (1 paper, 2024). "These brothers do not suffer from sensorineural hearing loss, a feature of some patients with type 4 Bartter syndrome (e.g., with mutations in the common chloride channel cofactor Barttin, or digenic mutations in ClC-Ka and ClC-Kb)." (PMID 39405114, 2024).
tumor (7 papers, 2010 to 2025). "In the correlation of tumor-infiltrating lymphocytes (TILs) with DEGs, we found that CLC and GFI1 were significantly associated with immune cells." (PMID 36188575, 2022). "The CLC gene differentiates the tumor groups the most with regard to mRNA expression levels (P = 0.001)." (PMID 20459617, 2010).
cancer (4 papers, 2018 to 2022). A tumor composed of atypical neoplastic, often pleomorphic cells that invade other tissues. "CLC2 exons containing a cancer SNP are less conserved than CLC2 exons overall, and display a conservation level comparable to non-CLC exons." (PMID 34316704, 2021).
infection (4 papers, 2016 to 2025). The state of being infected such as from the introduction of a foreign agent such as serum, vaccine, antigenic substance or organism. "Two proteins, carbonic anhydrase I (CA1) and Charcot-Leyden crystal galectin (CLC) are common interacting targets of TRP120 and TRP47, suggesting their importance during infection." (PMID 28553621, 2017).
inflammation (3 papers, 2016 to 2023). Aberrant reaction of the microcirculation characterized by movement of fluid and leukocytes from the blood into extravascular tissues. "Elsewhere, elevated CLC/Gal‐10 levels have been measured as a biomarker of active eosinophilic inflammation that strongly correlates with the number of esophageal eosinophils in eosinophilic oesophagitis." (PMID 37283884, 2023). "CLC/Gal-10 is also a potential biomarker for eosinophilic airway inflammation in induced sputum." (PMID 26904159, 2016).
neurological diseases (3 papers, 2022 to 2023). "Modulation of inflammatory responses by CLC-type transporter functions may be responsible for the severe phenotype of engineered animal models and may contribute to symptom severity in patients with CLC-linked neurological diseases." (PMID 37124866, 2022). "Structure-based studies of the ClC-6 Cl-/H+ exchanger provide insight into CLC gating and its alteration in neurological disease." (PMID 37831762, 2023). "List of the CLC genes, subcellular localization and CLC related neurological diseases." (PMID 37374100, 2023).
genetic diseases (1 paper, 2017). "Phenotypes of mouse models have linked ClC protein function and dysfunction with inherited human genetic diseases." (PMID 28386229, 2017).
CLC also shares sentences with these, for which no sentence is quoted: Allergy (6 papers); chronic rhinosinusitis (4); atopic dermatitis (3); celiac disease (3); eosinophilic diseases (3); eosinophilic esophagitis (3); respiratory disease (3); allergic asthma (2); eosinophilic granulomatosis with polyangiitis (2); gestational diabetes (2); hypereosinophilic disease (2); mesothelioma (2); Miscarriage (2); Myotonia (2); osteosarcoma (2); abortion (1); Achalasia (1); acute myeloid leukemia (1); amoebic dysentery (1); autoimmune disorder (1); Bartter syndrome (1); Bartter Syndrome Type III (1); Behçet syndrome (1); bullous pemphigoid (1); cardiovascular diseases (1); cervical carcinoma (1); childhood asthma (1); cleft lip (1); cleft palate (1); colitis (1).
A further 33 diseases each share a sentence with CLC in 1 paper.